CTSL (cathepsin L)
Diseases named in the same sentence as CTSL in open-access papers (continued):
Sharing a sentence is not in itself a finding about the gene and the disease.
laryngeal carcinoma (2 papers, 2025). Carcinoma that arises from the laryngeal epithelium. "We validated the association of CTSL with the prognosis and autophagy of laryngeal cancer across multiple cohorts." (PMID 39893643, 2025). "The cell lines overexpressing CTSL exhibited significantly increased mRNA levels of these proliferation‐related markers, further confirming the close association between laryngeal cancer cell proliferation and CTSL expression." (PMID 39893643, 2025). "Concurrently, CTSL is closely associated with the autophagic levels in laryngeal cancer cells." (PMID 39893643, 2025). "In starving laryngeal cancer cells undergoing autophagy, CTSL expression shows an increasing trend at different time points, providing further evidence of the close association between CTSL and the autophagic levels in laryngeal cancer cells." (PMID 39893643, 2025). "This risk stratification could guide treatment strategies, and future studies could further explore the relationship between CTSL, this risk score and immune response and treatment outcomes in laryngeal cancer patients." (PMID 39893643, 2025). "In this study, we investigated whether CTSL is involved in the regulation of autophagy in laryngeal cancer cells and the associated mechanisms." (PMID 39893643, 2025). "Western blot experiments also reveal differences in the protein expression of the autophagy‐related marker p62, LC3b in laryngeal cancer cell lines with CTSL knockdown and overexpression." (PMID 39893643, 2025). "Subsequently, we performed Opal Multiplex Immuno‐Histochemistry on tissue sections from laryngeal cancer patients and found a close relationship between CTSL and IL6, JAK and STAT3." (PMID 39893643, 2025). "Following the manipulation of CTSL expression in normal laryngeal cells and laryngeal cancer cells, we monitored the expression of mRNA and proteins in the IL6‐JAK‐STAT3 pathway." (PMID 39893643, 2025). "The proliferation of laryngeal cancer cells relies on the expression of CTSL, with overexpression of this gene enhancing the proliferative capacity of these cells." (PMID 39893643, 2025). "CTSL is significantly upregulated in laryngeal cancer tissues, its elevated levels are indicative of poor prognosis in patients with laryngeal cancer." (PMID 39893643, 2025). "In summary, we found that CTSL promotes autophagy in laryngeal cancer through the IL6‐JAK‐STAT3 signalling pathway." (PMID 39893643, 2025). "Immunohistochemical staining of laryngeal cancer tissue also suggests that the area of CTSL‐positive cells is high in laryngeal cancer tissue." (PMID 39893643, 2025). "We found that CTSL upregulates autophagy in laryngeal cancer cells by activating the IL6‐JAK‐STAT3 signalling pathway." (PMID 39893643, 2025). "This study has certain limitations, such as not thoroughly investigating the specific reasons for the upregulation of CTSL in laryngeal cancer." (PMID 39893643, 2025). "Compared to the control group, tumours induced by CTSL‐knockdown TU212 laryngeal cancer cells exhibited significant reduction in size, indicating that downregulation of CTSL can decrease tumour volume in vivo." (PMID 39893643, 2025). "Scratch assays indicated that CTSL knockdown reduced the migration ability of laryngeal cancer cells, whereas CTSL overexpression increased their migration capability." (PMID 39893643, 2025). "We observed a significant upregulation of CTSL in laryngeal cancer tissues, and its elevated levels are indicative of poor prognosis in laryngeal cancer patients." (PMID 39893643, 2025). "In conclusion, our study suggests that CTSL promotes autophagy in laryngeal cancer by regulating the IL6‐JAK‐STAT3 signalling pathway." (PMID 39893643, 2025). "Both mRNA and protein expression levels of CTSL in laryngeal cancer specimens were significantly higher than those in adjacent normal tissues." (PMID 39893643, 2025). "Upregulation of CTSL facilitated autophagy in laryngeal cancer cells, whereas downregulation had inhibitory effects." (PMID 39893643, 2025).
laryngeal carcinoma (continued). "We found that CTSL regulates the IL‐6‐JAK‐STAT3 signalling pathway to enhance autophagy in laryngeal cancer." (PMID 39893643, 2025). "Transwell assays demonstrated that CTSL knockdown weakened the invasive capacity of laryngeal cancer cells, while CTSL overexpression enhanced their invasive ability." (PMID 39893643, 2025). "We measured the expression levels of CTSL in specimens from human laryngeal cancer and adjacent normal tissues." (PMID 39893643, 2025). "Our previous studies found that CTSL promoted laryngeal cancer autophagy through the IL6‐JAK‐STAT3 signalling pathway." (PMID 41261048, 2025). "Although we have elucidated the mechanism by which CTSL promotes autophagy in laryngeal cancer cells by activating the IL6‐JAK‐STAT3 signalling pathway at the molecular and genetic levels, increasing evidence suggests that cancer represents a complex pathological ecosystem." (PMID 39893643, 2025). "Furthermore, upregulation of CTSL promoted the proliferation and invasion of laryngeal cancer cells, while downregulation had inhibitory effects on tumour growth." (PMID 39893643, 2025). "Furthermore, we elucidated that CTSL promotes laryngeal cancer progression through the IL6‐JAK‐STAT3 signalling pathway." (PMID 41261048, 2025). "Furthermore, by considering the autophagy regulatory role of CTSL, we established an autophagy‐related signature, enhancing the ability of CTSL to predict the prognosis and drug sensitivity of laryngeal cancer." (PMID 39893643, 2025). "Furthermore, at the cellular level, the protein and mRNA expression levels of CTSL showed higher expression in laryngeal cancer cells compared to normal laryngeal cells." (PMID 39893643, 2025). "Furthermore, the integration of CTSL with autophagy‐related genes as a multi‐gene biomarker demonstrates strong predictive power for the prognosis of laryngeal cancer, holding significant clinical utility." (PMID 39893643, 2025). "This study aims to explore the role of CTSL in laryngeal cancer and its clinical significance." (PMID 39893643, 2025). "Despite CTSL being reported to regulate BPs in many tumours, its role in laryngeal cancer remains unclear." (PMID 39893643, 2025). "Additionally, immunohistochemistry (IHC) confirmed that the levels of IL6 and LC3b in the CTSL‐knockdown group were significantly lower than those in the control group, further suggesting that CTSL promotes laryngeal cancer autophagy through the IL6‐JAK‐STAT3 signalling pathway." (PMID 39893643, 2025). "Knockdown of IL6 weakened the autophagy of CTSL‐overexpressing laryngeal cancer cells, while the addition of recombinant IL6 protein enhanced autophagy in CTSL‐overexpressing cells." (PMID 39893643, 2025). "The data analysis of the TCGA‐HNSC reveals a positive correlation between the expression of CTSL and autophagy‐related markers such as ATG5, ATG7, ATG12, ATG16L and LC3b, suggesting a connection between CTSL and autophagy in laryngeal cancer." (PMID 39893643, 2025). "Similarly, in laryngeal cancer cells TU212 and TU686, stable transfectants with high CTSL expression exhibited an increase in IL6‐JAK‐STAT3 pathway activity, while low expression stable transfectants showed a decrease." (PMID 39893643, 2025). "After constructing stable cell lines with CTSL knockdown and overexpression using recombinant lentivirus, CCK‐8 assays were employed to validate the impact of CTSL expression on the proliferation of laryngeal cancer cells." (PMID 39893643, 2025). "To further investigate whether CTSL promotes autophagy in laryngeal cancer through the IL6‐JAK‐STAT3 signalling pathway, we knocked down IL6 in CTSL overexpression stable transfectants." (PMID 39893643, 2025). "Interestingly, we found that CTSL promotes autophagy in laryngeal cancer through the IL6‐JAK‐STAT3 pathway, but IL6 does not affect CTSL expression." (PMID 39893643, 2025).
lung adenocarcinoma (2 papers, 2022 to 2024). A carcinoma that arises from the lung and is characterized by the presence of malignant glandular epithelial cells. "We assess the effect of lung adenocarcinoma cells on TAM through detecting the expression of SHP2, p- STAT1, p-STAT3, p-STAT5, p-STAT6, IL-4, IL-10, Cathepsin-L, Cathepsin-S, Cathepsin-K and Arginase-1 in each group of THP1 cells cocultured with and without A549 cells by western blot." (PMID 38747738, 2024). "Additionally, there existed statistically significant differences in CTSL expression levels among the different stages of ESCA, STAD, BLCA, KIRC, and lung adenocarcinoma (LUAD)." (PMID 35155389, 2022).
malaria (2 papers, 2008 to 2009). Malaria is a serious and sometimes fatal disease caused by a parasite that commonly infects a certain type of mosquito which feeds on humans. "The S2 pocket of longipain contains Asp332, like the human malaria parasite cathepsin L. Longipain was found to be most similar in sequence architecture to the known spider cathepsin B from Araneus ventricosus, with 64 % similarity." (PMID 18483546, 2008).
muscle atrophy (2 papers, 2022 to 2024). The loss of muscle tissue due to inactivity or disease. "FOXO1 also activates the expression of atrophy-related genes such as Atrogin 1 and cathepsin L in various muscle atrophy-related conditions." (PMID 36386197, 2022). "Furthermore, their downstream genes such as FBXO32, TRIM63, CTSL, and BNIP3, which have been associated with skeletal muscle atrophy in humans and mice, were found to be significantly upregulated in G. parasuis-infected skeletal muscle." (PMID 38540418, 2024).
mycoplasma pneumonia (2 papers, 2016 to 2019). "This dichotomy is exemplified by cathepsin L (CTSL), which helps Hendra virus and SARS coronavirus to invade cells, but is essential for survival in mice with mycoplasma pneumonia." (PMID 27716790, 2016).
myocardial ischemia (2 papers, 2017 to 2024). A disorder of cardiac function caused by insufficient blood flow to the muscle tissue of the heart. "Interestingly, six out of the seven most differentially expressed IZ genes (IL8, ARG1, S100A12, CTSL, IL1R2, S100A8) identified in our study have been previously reported in myocardial ischemia, confirming the validity of our chip analysis." (PMID 28977827, 2017).
non-small cell lung carcinoma (2 papers, 2022 to 2025). A group of at least three distinct histological types of lung cancer, including non-small cell squamous cell carcinoma, adenocarcinoma, and large cell carcinoma.
renal failure (2 papers, 2022 to 2025). "Hydroxychloroquine (HCQ) reduces renal insufficiency by downregulating NLRP3 inflammasomes activation mediated by CTSB and CTSL." (PMID 36209090, 2022).
squamous cell carcinoma (2 papers, 2019 to 2020). A carcinoma arising from squamous epithelial cells. "Additionally, the expression of CTSL progressively increased with increasing malignancy grade in squamous cell carcinoma (SCC) (P < 0.01), while not evident in adenocarcinoma (ADC)." (PMID 30732622, 2019).
synucleinopathies (2 papers, 2023 to 2025). "Taken together, our data confirm that externally administered cysteine proteases CTSB and CTSL promote the clearance of SNCA species in vitro, ex vivo as well as in vivo, providing a new therapeutic approach for the treatment of synucleinopathies." (PMID 40883786, 2025).
Type 2 Diabetes (2 papers, 2020 to 2021). "Additionally, the protein abundance and enzymatic activity of CTSL in endothelial progenitor cells (EPCs) isolated from type 2 diabetic patients were merely 50% of those in the EPCs isolated from health controls." (PMID 33293479, 2020).
uremia (2 papers, 2013 to 2015). A clinical syndrome associated with the retention of renal waste products or uremic toxins in the blood. "Our results were corresponds to a previous study that the mRNA expressions of LC3, GabarapI1, and Cathepsin L were upregulated in the skeletal muscle of uremia rats induced by subtotal nephrectomy and by type 2 diabetic nephropathy." (PMID 26448817, 2015).
worm infection (2 papers, 2014). "Here we demonstrate that sub-cutaneous injection of functionally active S. mansoni cathepsin B1 (SmCB1), or a cathepsin L from a related parasite Fasciola hepatica (FhCL1), elicits highly significant (P<0.0001) protection (up to 73%) against an experimental challenge worm infection." (PMID 24465551, 2014).
adenoma (1 paper, 2021). A neoplasm arising from the epithelium. "Finally, by performing an in silico analysis, we describe the mRNA expression of ACE2, TMPRSS2 and the genes encoding their co-receptors CTSB, CTSL and FURIN in normal adrenal and adrenocortical tumors (both adenomas and carcinomas)." (PMID 34594302, 2021).
alcoholic liver diseases (1 paper, 2011). A disorder caused by damage to the liver parenchyma due to alcohol consumption. "Therefore, reduction in CTSL levels by acetaldehyde observed in the present study may explain the formation of new vessels that are closely associated with the pattern of fibrosis development typical of alcoholic liver disease." (PMID 21687683, 2011).
amyloidosis (1 paper, 2016). A disorder characterized by the localized or diffuse accumulation of amyloid protein in various anatomic sites. "The overlapping expression of H3K4 me3 and cathepsin L in patients with nephrotic syndrome diagnosed as minimal change (N = 2) and FSGS (N = 2) and amyloidosis (N = 3) were examined." (PMID 27855638, 2016).
anaplastic glioma (1 paper, 2012). "Besides invasion, Cathepsin L may play a role in decreased susceptibility of anaplastic glioma cells to apoptosis." (PMID 22995409, 2012).
Arrhythmia (1 paper, 2023). Any cardiac rhythm other than the normal sinus rhythm. "On the contrary, all the otherbiomarkers (Galectin-3, Cathepsin-L and Caspase-3) demonstrated a significantdecline in all patients regardless of the arrhythmia outcome during long-termfollow-up." (PMID 39077532, 2023).
Arthritis (1 paper, 2013). Inflammation of a joint. "By using T cells isolated from arthritis patients, we demonstrated that increased CTSL-mediated activation of C3 is connected with uncontrolled pathological effector T cell function." (PMID 24315997, 2013).
ascariasis (1 paper, 2018). An infection that is caused by the roundworm Ascaris lumbricoides, many cases of which remain asymptomatic. "Also our antigen did not cross-react with ascariasis patient sera, further distinguishing it from the recombinant cathepsin L." (PMID 29843786, 2018).
asthenozoospermia (1 paper, 2024). "Histone H4, cathepsin L, glutathione synthetase, and ENO1 emerged as potential biomarkers for asthenozoospermia." (PMID 38605082, 2024). "Furthermore, proteins histone H4, cathepsin L, glutathione synthetase and ENO1 are proposed as potential biomarkers of autophagy and vitality in asthenozoospermia sperm." (PMID 38605082, 2024).
bacterial pneumonia (1 paper, 2021). Acute infection of the lung parenchyma caused by bacteria (e.g., Streptococcus pneumoniae, Haemophilus influenzae, Chlamydia pneumoniae, Mycoplasma pneumoniae, and Legionella pneumophila). "When COVID-19 pneumonia patients and bacterial pneumonia or healthy controls were compared, CTSL was upregulated in monocytes, macrophages, neutrophils, and epithelial cells in COVID-19 pneumonia patients." (PMID 34497809, 2021).
Batten disease (1 paper, 2020). "The two Batten disease proteins that do not contain putative CaMBDs are potentially linked to CaM through their association with cathepsin L, which contains a putative CaMBD." (PMID 31774219, 2020).
Brain atrophy (1 paper, 2024). Partial or complete wasting (loss) of brain tissue that was once present. "However, CTSB also possesses neuroprotective and anti-amyloidogenic properties, and mice studies have revealed neuronal loss and brain atrophy in double-KO mice lacking both CTSB and CTSL." (PMID 39286235, 2024).
brain infarct (1 paper, 2022). "Additionally, injection of a cathepsin L inhibitor significantly reduced brain infarct size and improved functional scores." (PMID 41541591, 2022).
Cachexia (1 paper, 2025). Severe weight loss, wasting of muscle, loss of appetite, and general debility related to a chronic disease. "Several features associated with cachexia, such as loss of muscle mass, skeletal muscle expression of Cathepsin L and LC3, as well as markers of intestinal permeability and immune function, showed slight improvements following synbiotic administration." (PMID 39764565, 2025).
cervical squamous cell carcinoma (1 paper, 2020). A squamous cell carcinoma arising from the cervical epithelium. "In addition, ACE2 and CTSL/B are overexpressed in the IFN-gamma immune subtype of ovarian serous Cystadenocarcinoma (OV), Cervical squamous cell carcinoma and endocervical adenocarcinoma (CESC), and Bladder urothelial carcinoma (BLCA)." (PMID 33231569, 2020).
cervical tumor (1 paper, 2022). "Transcriptomics analysis of primary cervix tumor samples and genetic knock out demonstrates a role for the lysosomal protease cathepsin L in radiation-induced cell death in SERPINB3 knock-out cells." (PMID 35022555, 2022). "Guided by expression patterns in primary cervix tumor samples, we identified cathepsin L as at least one of the cysteine protease targets of SERPINB3 in cervical tumor cells that mediates radiation-induced cell death in the absence of SERPINB3." (PMID 35022555, 2022). "Additionally, the SERPINB3 RSL is required for protection against radiation, and knockout of the lysosomal cysteine protease cathepsin L (CTSL) partially protected SERPINB3-KO cervix tumor cells from radiation-induced death, further supporting the mechanism of lysosomal protease inhibition." (PMID 35022555, 2022). "Therefore, we hypothesized that CTSL was the most-likely target of SERPINB3 in cervix tumor cells and generated stable knockout cell lines using CRISPR-Cas9 targeting of CTSL in the SW756-B3-WT and –B3-KO backgrounds." (PMID 35022555, 2022).
chronic cholecystitis (1 paper, 2019). "Having established increased activities of both CTSL and CTSB in GBC as compared to control gallbladder with chronic cholecystitis, we then sought to examine the diagnostic potential of these cathepsins in GBC using ROC analysis." (PMID 31824841, 2019). "In the present study, we have demonstrated a significant increase in the serum levels of CTSL and CTSB in GBC patients as compared to their levels in chronic cholecystitis and healthy controls." (PMID 31824841, 2019).
cognitive impaired (1 paper, 2024). "In observational cohort, we found there was decreased blood CTSL expression level in Aβ+ cognitive impaired (CI) group, compared with Aβ− cognitive unimpaired (CU) group." (PMID 39559895, 2024).
colorectal adenoma (1 paper, 2021). An adenoma that arises from the colon or rectum. "Single-cell transcriptome analyses of colon mucosae of normal, colorectal adenoma (CRA), and colorectal cancer (CRC) patients have shown increased expression of SARS-CoV2 entry-related genes such as ACE2, CD147 (Basigin), TMPRSS2, Cathepsin B (CATB), Cathepsin L (CATL), and Furin." (PMID 34760721, 2021).
colorectal tumor (1 paper, 2022). "In colorectal tumor-bearing mice, markers of increased lysosomal activation, including cathepsin L, beclin, and microtubule-associated protein light chain 3 (LC3), were elevated in the myocardium." (PMID 35326491, 2022).
cystic fibrosis (1 paper, 2024). Autosomal recessive disorder caused by pathogenic variants in the CFTR gene (cystic fibrosis transmembrane conductance regulator), which encodes a chloride and bicarbonate channel expressed in epithelial cells, and follow the diagnosis criteria. "CTSB, CTSL, and CTSS are overexpressed in lung tissues of patients with cystic fibrosis." (PMID 39559762, 2024).